HLA-DRB1 (major histocompatibility complex, class II, DR beta 1)
Diseases named in the same sentence as HLA-DRB1 in open-access papers (continued):
Sharing a sentence is not in itself a finding about the gene and the disease.
atherosclerosis (5 papers, 2012 to 2024). A disease characterized by the build-up of fatty material and calcium deposition in the arterial wall resulting in partial or complete occlusion of the arterial lumen. "In addition, HLA was associated with the development of atherosclerosis Moreover, HLA-DRB1 alleles were previously reported to define the shared genetic relationship between RA and atherosclerosis." (PMID 38892172, 2024). "Nevertheless, several other studies, including one with Latin American patients, have found evidence that the HLA-DRB1 gene, especially the*04 alleles, may play a role in endothelial activation, accelerated atherosclerosis and high mortality due to CVD." (PMID 22912672, 2012).
colorectal cancer (5 papers, 2020 to 2024). A primary or metastatic malignant neoplasm that affects the colon or rectum. "We identified 33 hub proteins between Colorectal Cancer and other diseases, with P01911 (encoded by the HLA-DRB1 gene) being the most frequently occurring protein (7 times)." (PMID 38674412, 2024). "Association between heterozygosity at HLA Class I loci (HLA-A, -B, and –C), Class II loci (HLA-DRB1, DQB1, and DPB1) and susceptibility to colorectal cancer." (PMID 37942321, 2023).
glioma (5 papers, 2015 to 2024). A benign or malignant brain and spinal cord tumor that arises from glial cells (astrocytes, oligodendrocytes, ependymal cells). "The results of the DEG co-expression network showed that the HLA family (HLA-A, HLA-B, HLA-C, HLA-E, HLA-DRA, HLA-DRB1, and CD74 [HLADG]) plays a vital role in the network, suggesting that tumor immunity is involved in glioma formation." (PMID 34660294, 2021).
Hashimoto thyroiditis (5 papers, 2010 to 2024). An autoimmune disorder caused by the production of autoantibodies against thyroid tissue. "Furthermore, thyroid autoantigen presentation to T cells, which can result in autoimmune thyroid disorders like Hashimoto’s thyroiditis, is significantly influenced by HLA-DRB1 alleles." (PMID 39063437, 2024).
Hypertension (5 papers, 2021 to 2024). The presence of chronic increased pressure in the systemic arterial system. "The HLA-DRB1 genotype has been associated with increased autoantibody production against angiotensin AT1 receptors, which might cause predisposition to the development of hypertension." (PMID 39062101, 2024).
hypothyroidism (5 papers, 2013 to 2024). Abnormally low levels of thyroid hormone. "For hypothyroidism, the strongest 4-digit allelic associations were seen at the HLA-DQA1*0501, HLA-DQB1*0201, HLA-DRB1*0301 alleles (P<10−6 for each allele), which collectively comprise the HLA-DR3-DQ2 haplotype." (PMID 27109359, 2016).
lung carcinoma (5 papers, 2017 to 2024). "No recurrent MET fusions were identified, some of the fusion partners included HLA-DRB1-MET (lung cancer), CD47 (lung cancer), CAPZA2 (gastric cancer), AKAP9 (hepatobiliary cancer), CLIP2 (hepatobiliary cancer), and SLC25A19 (ovarian cancer)." (PMID 36369474, 2022). "Until recently, MET fusion, such as KIF5B-MET, MET-ATXN7L1, and HLA-DRB1-MET had mainly been reported in lung cancer." (PMID 36483096, 2022). "In particular, we identified two lung cancer cases, one (PT218) with an HLA-DRB1-MET fusion gene and the other (PT230) with an IRF2BP2-NTRK1 fusion gene." (PMID 36369474, 2022).
lupus nephritis (5 papers, 2006 to 2023). Glomerulonephritis in the context of systemic lupus erythematosus. "The aim of this study was to investigate, for the first time, the association of HLA-DRB1 and HLA-DQB1 genes among Jordanian patients diagnosed with SLE and Lupus Nephritis (LN) using the Polymerase Chain Reaction-Sequence-Specific Primer (PCR-SSP) technique." (PMID 36556176, 2022). "We found significantly higher frequency of HLA-DRB1*13 (OR = 5.1; 95% CI, 1.7 to 15.4; P = 0.03) and development of end-stage renal disease (OR = 5.8; 95% CI, 1.7 to 19.7; P = 0.008) in hAPLN compared with lupus nephritis." (PMID 25927214, 2015). "Similarly, the absence of an association of HLA-DRB1, HLA-DQB1, and HLA-DQA1 alleles with renal involvement in our cohort may represent a power issue for HLA-DRB1*15 (HLA-DR2) and other alleles previously reported to be associated with lupus nephritis." (PMID 17076550, 2006).
nephritis (5 papers, 2013 to 2025). Inflammation of renal tissue. "The analysis of high-resolution HLA typing results in addition to the division of patients into subgroups according to the presence of GI involvement and nephritis revealed several additional HLA-DRB1 alleles demonstrating association with IgAV." (PMID 38255953, 2024). "It was characterized by a distinct biomarker profile (including higher IFNγ levels), earlier disease onset, and more nephritis and was the only cluster associated to HLA-DRB1*15, indicating that we may be dealing with a distinct SLE subset." (PMID 38460182, 2025). "For example, HLA-DQB1*03 seems to be related with skin manifestations, HLA-DRB1*15 with nephritis, DRB1*10 with hematological manifestations, and HLA-DRB1*11 with neurological manifestations." (PMID 33528690, 2021). "The increase in HLA-DRB1*10:01 allele frequency among IgAV and GI patients and -DRB1*14:01P allele frequency among IgAVN patients were also significant in comparison to those observed among patients without GI involvement and nephritis (p = 0.0050 and p = 0.0242, respectively)." (PMID 38255953, 2024).
neuromyelitis optica (5 papers, 2014 to 2025). A rare inflammatory disease of the central nervous system characterized mainly by attacks of uni- or bilateral optic neuritis (ON) and acute myelitis. "Recently, we reported that HLA-DRB1*0405 and HLA-DPB1*0301 are susceptibility alleles, while DRB1*0901 and DPB1*0401 are protective alleles for Japanese MS when neuromyelitis optica (NMO) and NMO spectrum disorder (NMOSD) patients are excluded." (PMID 24736746, 2014).
Pruritus (5 papers, 2022 to 2024). Pruritus is an itch or a sensation that makes a person want to scratch. "A variation in HLA-DRB1 was found to be associated with one or more types of cirAEs, and a more detailed association between HLA-DRB1*11:01 and pruritus was validated." (PMID 37497220, 2023). "Among cutaneous irAEs, 102 patients with metastatic cancer who received ICIs treatment were significantly associated with HLA-DRB1*11:01 and pruritus (OR = 4.53, X2 1,95 = 9.45, P < 0.01)." (PMID 36891313, 2023). "Few biological markers such as rheumatoid factor (RF) greater than 15 IU/ml at baseline and the presence of an HLA-DRB1*11:01 genotype are emerging as potential predictive biomarkers of skin toxicity, especially in case it is associated with pruritus, in patients treated with ICI-based treatment." (PMID 36713496, 2022).
pulmonary TB (5 papers, 2016 to 2022). "Among the most frequently found alleles, HLA-DRB1*15, present in at least 10% of allfive populations, is associated with a higher incidence of active pulmonary TB andhas been considered a possible marker of disease development." (PMID 34320128, 2021). "Recent reports have associated the HLA-DRB1*04:11 allele with an increased susceptibility to pulmonary tuberculosis in Amazon Brazilian population." (PMID 32094421, 2020). "In conclusion, the present study showed HLA-DRB1*04 genes and their subtypes associated with pulmonary TB." (PMID 26901036, 2016). "The combination of HLA-DRB1*04 gene and alcohol consumption increased twice as much the risk for pulmonary TB development." (PMID 26901036, 2016). "HLA-DRB1*04 showed strong association with susceptibility to pulmonary TB (p<0.0001; OR = 2.94; 95% CI = 2.12 to 4.08)." (PMID 26901036, 2016). "The subtype HLA-DRB1*04:11:01 (p = 0.0019; OR = 2.23; 95% CI = 1.34 to 3.70) was associated with susceptibility to pulmonary TB while DRB1*04:07:01 (p<0.0001; OR = 0.02; 95% CI = 0.001 to 0.33) to protection." (PMID 26901036, 2016). "HLA-DRB1*04:11:01 was strongly associated with susceptibility to pulmonary TB (p = 0.0019; OR = 2.23, 95% CI = 1.34 to 3.70)." (PMID 26901036, 2016). "A study conducted in Recife, Northeast Brazil, also identified HLA-DRB1*04 associated with pulmonary TB." (PMID 26901036, 2016). "It is highly probable that this is the allele associated with protection in Mexico since the generic HLA-DRB1*04 was associated with protection against pulmonary TB." (PMID 26901036, 2016). "We analyzed the HLA-DRB1*04 alleles to identify subtypes associated with pulmonary TB and their interaction with risk factors such as alcohol, smoking, and gender in 316 pulmonary TB patients and 306 healthy individuals from the Brazilian Amazon." (PMID 26901036, 2016). "Distribution and association analysis of HLA-DRB1*04 subtypes in pulmonary TB patients and the control group." (PMID 26901036, 2016). "For this reason, our study aimed to identifying subtypes of HLA-DRB1*04 in patients with pulmonary TB to correlate with risk factors for the development of disease and to explain the HLA role on the high incidence rate of TB cases in the Amazonas state." (PMID 26901036, 2016). "In this study, the generic HLA-DRB1*04 allele was most common in pulmonary TB patients, showing strong association with susceptibility to disease." (PMID 26901036, 2016). "Only the interaction of alcohol (p = 0.0001; OR = 51.3; 95% CI = 6.81 to 386) with HLA-DRB1*04:11:01(p = 0.0265; OR = 2.13; 95% CI = 1.09 to 4.14) showed a very high risk of susceptibility to pulmonary TB." (PMID 26901036, 2016). "In a study to analyze HLA-DRB1, DQA1 and DQB1 allelic polymorphism in Iranian patients with pulmonary TB, HLA-DRB1*07 and HLA-DQA1*0101 alleles apparently conferred susceptibility to TB while HLA-DQA*0301 and HLA-DQA*0501 conferred protection against this infection." (PMID 26803588, 2016). "Notably, the interaction between alcohol and HLA-DRB1*04:11:01 increased the risk for developing pulmonary TB (p = 0.0001; OR = 51.3; 95% CI = 6.81 to 386)." (PMID 26901036, 2016). "The number of individuals with the HLA-DRB1*04:07:01 or HLA-DRB1*04:92 is small, therefore, require more research with larger numbers of patients with pulmonary TB and controls." (PMID 26901036, 2016). "Of the 622 individuals participating in the study, 288 were positive for HLA-DRB1*04, 187 pulmonary TB patients (59.2%; 187/316) and 101 controls (33.0%; 101/306)." (PMID 26901036, 2016). "The HLA-DRB1*04 was prevalent in patients with pulmonary TB (p<0.0001; OR = 2.94; 95% CI = 2.12 to 4.08)." (PMID 26901036, 2016). "In preliminary studies, the generic HLA-DRB1*04 was frequent in pulmonary TB patients (unpublished data), but this gene has many subtypes and is very important to determine which alleles are associated with the disease." (PMID 26901036, 2016).
pulmonary TB (continued). "HLA-DRB1*04 (p = 0.0143; OR = 1.92; 95% CI = 1.14 to 3.23) showed strong interaction with alcohol (p< 0.0001; OR = 8.43; 95% CI = 3.85 to 18.5) and increased the significant risk for development of pulmonary TB when compared to non-carriers of the allele." (PMID 26901036, 2016).
rheumatic diseases (5 papers, 2010 to 2024). "HLA-DRB1 alleles are major determinants of genetic predisposition to rheumatic diseases." (PMID 28899403, 2017). "Although recent comprehensive genetic analyses have shown that HLA-DRB1 polymorphisms are associated with rheumatic diseases and poor prognosis, they have not yet been applied as diagnostic markers because other genetic and environmental factors may also be involved." (PMID 35330444, 2022).
systemic juvenile idiopathic arthritis (5 papers, 2020 to 2024). "The systemic juvenile idiopathic arthritis (juvenile-onset Still's disease) has multiple-gene predisposition, including HLA-DRB1." (PMID 32149159, 2020). "Additionally, given the reported association between cytokine-like IL-1 and IL-6 inhibitors and HLA-DRB1*15 alleles in DRESS cases with Still’s disease, we should also explore the role of cytokines in these adverse reactions." (PMID 39188942, 2024).
bipolar affective disorders (4 papers, 2016 to 2025). "A recent GWAS demonstrated that the genetic diversity of HLA-DRB1 and HLA-DQB1 alleles modulates responses to treatment with lithium-containing drugs in bipolar affective disorders." (PMID 41155473, 2025).
Brain atrophy (4 papers, 2017 to 2023). Partial or complete wasting (loss) of brain tissue that was once present. "Second, although significant brain atrophy has been observed in GWI, HLA-DRB1*13:02 has been shown to protect against brain atrophy in Gulf War veterans." (PMID 31031617, 2019). "The purpose and structure of HLA-DRB1*13:02 provides some insights into the mechanisms that may confer protection against brain atrophy, as observed here." (PMID 29452862, 2018).
encephalitis (4 papers, 2020 to 2021). An acute inflammatory process affecting the brain parenchyma. "Fourth, in East-Asian subject E133P with anti-NMDA receptor encephalitis, the C4B gene had a mutation that changed tryptophan-660 to a stop-codon (W660x), which was present in a haplotype with HLA-DRB1*04:06 and B*15:27." (PMID 34764957, 2021). "Over 90% of LGI1-antibody-positive encephalitis patients, of both East Asian and Caucasian extraction, have the HLA-DRB1*07:01allele, while patients with CASPR2-antibody encephalitis have a marked overrepresentation of HLA DRB1*11:0l." (PMID 31655889, 2021).
follicular lymphoma (4 papers, 2011 to 2024). Follicular lymphoma is a form of non-Hodgkin lymphoma characterized by a proliferation of B cells whose nodular structure of follicular architecture is preserved. "For other lymphoproliferative disorders apart of follicular lymphoma, scientists have discovered other strong protective associations like HLA-DRB1*04:01 for patients with DLBCL." (PMID 38535155, 2024). "While risk of diffuse large B-cell lymphoma and marginal zone lymphoma were increased with homozygosity of class I HLA-B and HLA-C loci and the class-II HLA-DRB1 locus, follicular lymphoma risk was associated with the increase in homozygous loci for HLA class II genes." (PMID 37942321, 2023). "Association (OR and 95% CI) for NHL, DLBCL, and follicular lymphoma for NHL-relevant risk factors (sunlight, environmental exposures), by HLA-DRB1*01:01 allele status and adjusted for age, education, sex, race, and study center." (PMID 22096508, 2011). "Association (OR and 95% CI) for NHL, DLBCL, and follicular lymphoma for NHL-relevant risk factors (family/medical history and anthropometrics/diet), by HLA-DRB1*01:01 allele status and adjusted for age, education, sex, race, and study center." (PMID 22096508, 2011). "We reported HLA-DRB1*01:01 as a novel susceptibility allele in NHL risk, particularly for the follicular lymphoma subtype, which was consistent with results from a genome-wide association study." (PMID 22096508, 2011).
Graves ophthalmopathy (4 papers, 2013 to 2024). An autoimmune disorder of the EYE, occurring in patients with Graves disease. "We observed a higher frequency of the HLADRB1*03 allele in young patients with Graves’ ophthalmopathy." (PMID 23544060, 2013). "Carriers of the HLADRB1*03 allele were significantly more common in young patients with Graves’ ophthalmopathy (p = 0.001)." (PMID 23544060, 2013).
hepatitis B (4 papers, 2021 to 2024). "Another allele with potential protective roles against hepatitis B infection in Romanians is HLA-DRB1*15:01:01, a finding consistent with research done on other populations." (PMID 38392185, 2024). "Several reports show that HLA-DRB1 leucine at position 26 displays a positive association with the HBV vaccine response, while arginine at position 4, aspartic acid at position 57, and tyrosine at position 60 and position 78 exhibit a strong protective effect against occult hepatitis B infection." (PMID 38392185, 2024). "All HLA-DRB1*09 negative and positive volunteers were randomly selected for immunogenicity test and were confirmed to be negative for common infectious diseases including hepatitis B, hepatitis C, syphilis, and HIV." (PMID 33452310, 2021).
keloid (4 papers, 2012 to 2024). An irregularly shaped, elevated mark on the skin caused by deposits of excessive amounts of collagen during wound healing. "Concerning the major histocompatibility complex, it was found an association between keloid and HLA-DRB1* 15 (among Caucasians), HLA-DQA1* and DQB1* (among Chinese)." (PMID 23259072, 2012). "Previous studies have identified significant correlations between specific Human Leukocyte Antigen (HLA) alleles, such as HLA-DRB1*15 and HLA-DQA1 and DQB1, and keloid formation, suggesting a genetic inclination towards keloid development." (PMID 39119435, 2024).
lung fibrosis (4 papers, 2021 to 2025). "Furthermore, HLA-DRB1*11 positivity, alongside ATAs and/or dcSSc, has been reported as the strongest risk factor for SSc associated pulmonary fibrosis in a United Kingdom cohort." (PMID 35754823, 2022). "Additionally, the protective role of HLA-DRB1*04:05 could be linked to a decreased susceptibility to pulmonary infections—both viral and bacterial—which are known to exacerbate lung fibrosis and contribute to disease progression." (PMID 40141400, 2025). "Mutations in the CHRM3, HLA-DRB1, PLAU, and SETD2 genes are closely linked to the pathogenesis of pulmonary fibrosis." (PMID 38575860, 2024). "Among the 226 analyzed genes, only HLA-DRB1 and HLA-DQB1 genes and their relationships with pulmonary fibrosis were previously analyzed." (PMID 33446833, 2021).
non-small cell lung carcinoma (4 papers, 2021 to 2025). A group of at least three distinct histological types of lung cancer, including non-small cell squamous cell carcinoma, adenocarcinoma, and large cell carcinoma. "The most polymorphic HLA-DRB1 alleles can influence the susceptibility, resistance and prognosis of non-small cell lung cancer (NSCLC)." (PMID 40502633, 2025). "HLA-DRB1 expression can predict the prognosis of patients with non-small cell lung cancer who receive PD-1/PD-L1 immune checkpoint blockade." (PMID 34490269, 2021). "Specific HLA alleles, such as HLA-DRB1*11:01, have been linked to immune-related pruritus, and HLA-DQB1*03:01 has previously been shown to be associated with irColitis in metastatic melanoma and non-small cell lung cancer (NSCLC)." (PMID 40155873, 2025).
ovarian carcinoma (4 papers, 2021 to 2026). A malignant neoplasm originating from the surface ovarian epithelium. "In anti-Yo positive cases, a specific susceptibility haplotype involving HLA-DRB1*13:01 and HLA-DQA1*01:03 has been reported, particularly in patients with ovarian cancer, whereas the HLA-DRB1*04:01 allele appears to be protective." (PMID 41562781, 2026). "MSLN was positively correlated with immunosuppressive genes in ovarian cancer, such as LGALS9, CD276, TMIGD2, CD200, TNFRSF14, and human leukocyte antigen (HLA)-related families including HLA-DRA, HLA-DRB1, HLA-DPA1, HLA-DMA, HLA-E, etc.." (PMID 35692779, 2022).
psoriatic arthritis (4 papers, 2008 to 2023). Joint inflammation associated with psoriasis. "Our aim was to investigate the role of HLA-Cw*06 and HLA-DRB1 genes (including SE) with psoriatic arthritis (PsA) susceptibility." (PMID 17728335, 2008).